SNORA7B (small nucleolar RNA, H/ACA box 7B)
Synonyms: ACA7B
Gene: Small nucleolar RNA gene on chromosome 3 (129,397,210 to 129,397,348, reverse strand). Ensembl gene ENSG00000207088.
Gene Ontology:
Biological process: RNA processing
Cellular component: nucleolus
Homologues: Orthologues: chimpanzee SNORA7B (99% identical), mouse Snora7a (88% identical), rat LOC120102637 (88% identical). Paralogues in human: SNORA7A (99% identical).
Diseases named in the same sentence as SNORA7B in open-access papers:
SNORA7B is named in the same sentence as 5 diseases in open-access papers, as found by Europe PMC text mining. Sharing a sentence is not in itself a finding about the gene and the disease. The quoted sentences say what the papers report.
breast carcinoma (1 paper, 2022). "This is consistent with earlier results linking the upregulation of SNORA7B with breast cancer and SNORA42 in lung cancer." (PMID 35047824, 2022).
breast tumors (1 paper, 2024). "SNORA7B has been reported up-regulated in breast tumors compared to normal tissue, and SNORD15A and SNORA71A have been found up-regulated in brain metastases." (PMID 38612790, 2024).
Parkinson disease (1 paper, 2024). A progressive degenerative disorder of the central nervous system characterized by loss of dopamine producing neurons in the substantia nigra and the presence of Lewy bodies in the substantia nigra and locus coeruleus. "Furthermore, the dysregulation of snoRNAs like SNORD118 and SNORA7B is observed in Parkinson’s disease (PD)." (PMID 39000310, 2024).
tumor (1 paper, 2019). "Thus, SNORA7B knockdown not only promotes cell proliferation but also significantly inhibits tumor metastasis in breast cancer cell lines." (PMID 31168298, 2019).
SNORA7B also shares sentences with these, for which no sentence is quoted: lung carcinoma (1 paper).